IL1B (interleukin 1 beta)
Diseases named in the same sentence as IL1B in open-access papers (continued):
Sharing a sentence is not in itself a finding about the gene and the disease.
endothelial dysfunction (continued). "To further investigate the molecular mechanism responsible for TMAO-induced endothelial dysfunction in aging, we measured expression of pro-inflammatory cytokines TNF-α, IL-1β, activity of eNOS, and levels of superoxide production in the aorta." (PMID 28611682, 2017). "In serum samples, we assessed inflammatory markers (IL-1β, TNF-RI, TNF-RII, sFas, sFasL, MMP-9, TIMP-1, and TGF-β1), endothelial dysfunction markers (sE-selectin, sICAM-1, and sVCAM-1), and volume-related marker (NT-proBNP)." (PMID 27034745, 2016). "The increased inflammatory cytokines, IL-1β, IL-6, and TNF-α, under diabetic conditions promote the progression of endothelial dysfunctions, neutrophil accumulation, and coagulation." (PMID 26633490, 2015). "Following acute or repetitive ischemic episodes, persistent immune activation-mediated through interleukin-6 (IL-6), interleukin-1β (IL-1β), and tumor necrosis factor-α (TNF-α)-promotes endothelial dysfunction, microvascular instability, and extracellular matrix remodeling." (PMID 42195345, 2026). "Hyperinsulinemia and dyslipidemia can activate innate immune cells, leading to the release of pro-inflammatory cytokines such as IL-1β, IL-6, and TNF-α, which in turn promote endothelial dysfunction, vascular stiffness, and sodium retention—key hallmarks of hypertension." (PMID 40944247, 2025). "It results in macrophage activation, release of pro-inflammatory cytokines (IL-1β, TNF-α), nitric oxide overproduction, and subsequent hypotension and endothelial dysfunction—phenomena previously observed in early clinical trials of cell-free Hb as an oxygen therapeutic." (PMID 41373848, 2025). "It is well established that EAT secretes pro-inflammatory cytokines (such as IL-1β, IL-6, and TNF-α) and pro-fibrotic adipokines (such as TGF-β), which exert paracrine effects on adjacent cardiomyocytes, promoting oxidative stress, endothelial dysfunction, and fibrosis." (PMID 41294813, 2025). "The inflammatory component involves cytokine cascades—particularly Interleukin 1 beta (IL-1β) and Tumor Necrosis Factor alpha (TNF-α)—which exacerbate endothelial dysfunction through the NF-κB-mediated upregulation of adhesion molecules and matrix metalloproteinases." (PMID 40507729, 2025). "Key findings include the persistent activation of innate and adaptive immune responses, elevated levels of proinflammatory cytokines [e.g., interleukin-1 beta (IL-1β), IL-6, and tumor necrosis factor alpha (TNF-α)], and evidence of endothelial dysfunction and microclot formation​​." (PMID 40821254, 2025). "In aged mice, the systemic inflammatory response (serum amyloid A, IL-1β, IL-2, eotaxin), kidney injury (urea), liver injury (ALT), and endothelial dysfunction induced by a relatively low dose of LPS (3 mg/kg) were all more pronounced as compared with young mice." (PMID 41291381, 2025). "Upon recruitment to inflamed endothelium via chemokines such as CXCL1 and CXCL8, neutrophils exacerbate vascular inflammation by releasing pro-inflammatory cytokines, including IL-1β, IL-8, and tumor necrosis factor-α (TNF-α), which amplify endothelial dysfunction and promote monocyte adhesion." (PMID 40217958, 2025). "This process activates these immune cells and induces the release of additional pro-inflammatory cytokines, i.e., IL1α, IL1β, TNFα, IFNγ, and IL17, which may exacerbate endothelial dysfunction and contribute to the degradation of the endothelial glycocalyx." (PMID 39596318, 2024). "The changes in blood flow and endothelial dysfunction in the liver microcirculation may be partially explained by increased levels of inflammatory mediators such as TNF-α, IL-1β, and chemokines." (PMID 39337863, 2024). "Consistent with previous studies, IL-1β induced endothelial dysfunction in non-pathological aortas from C57BL/6 mice." (PMID 37025617, 2023).
endothelial dysfunction (continued). "In the present study, we have evaluated whether a positive feedback of IL-1β in the NLRP3 inflammasome via NF-κB could promote human endothelial senescence in vitro and murine endothelial dysfunction in vivo." (PMID 35111374, 2022). "They suggested multiple inflammatory mediators such as tumor necrosis factor (TNF), caspase-1, IL-1β, and NOD-like receptor family pyrin domain containing 3 (NLRP3) inflammasome are produced during inflammaging, thereby resulting in BBB leakage and endothelial dysfunction." (PMID 36034144, 2022). "In this study, we evaluated if there is positive feedback of IL-1β on the NLRP3 inflammasome and whether this loop could promote human endothelial senescence in vitro, and endothelial dysfunction in vivo, using a murine experimental model." (PMID 35111374, 2022). "In addition, it has been well documented that inflammatory factors such as IL-1β, TNF-α, TGF-β, and endotoxins can induce endothelial dysfunction via EndMT." (PMID 34604359, 2021). "The endothelial dysfunction evoked by visfatin/eNampt infusion in vivo was also sensitive to both MCC 950 and anakinra treatments, suggesting that the NLRP3-inflammasome-driven tissular release of IL-1β is the final mediator of endothelial damage." (PMID 32214150, 2020). "Taken together, these data suggest that ATP induced increases in IL-1β may provide a further positive feedback loop for p38 MAPK activation and endothelial dysfunction." (PMID 31412063, 2019). "During RA, the increased expression of TNF-α, IL-1β, IL-6, adhesion molecules, angiotensin II type 1 receptor, and endothelin, together with a lower expression of NO, might contribute to SAH via endothelial dysfunction." (PMID 28103312, 2017). "Dh404 significantly attenuated endothelial dysfunction in diabetic Akita mice characterized by reduced contraction in response to phenylephrine and the downregulation of inflammatory genes (VCAM-1, ICAM-1, p65, IL-1β) and pro-oxidant genes (Nox1 and Nox2)." (PMID 28253885, 2017). "The role of the PPP was studied by treating the mesenteric microvessels with 6-ANAM; this drug did not affect the endothelial dysfunction induced by IL1β in normal glucose but prevented the potentiation observed in high glucose conditions." (PMID 27245224, 2016). "Moreover, Pearson’s correlation coefficient revealed that endothelial dysfunction significantly correlated with aortic expression of inflammatory markers, TLR-4, TNF-α and IL-1β." (PMID 25826421, 2015). "In addition, anakinra also blocked NADPH oxidase activation by IL-1β to the same extent than apocynin, further supporting the role for NADPH oxidase-derived superoxide anions as mediators of the cytokine-induced endothelial dysfunction." (PMID 25518980, 2014). "We selected a 2 h period of IL-1β treatment as it produced a selective concentration-dependent endothelial dysfunction, without affecting the contractile or relaxant responses of the vascular smooth muscle layer." (PMID 25518980, 2014). "In addition to phagocytosis, macrophages secrete a diversity of cytokines including IL-1β, IL-8, and TNF-α, which lead to endothelial dysfunction." (PMID 24718556, 2014). "Accordingly, higher levels of IL-10 and decreased levels of IL-1β, after VNS in our model, could have decreased hemorrhage induced endothelial dysfunction and also contributed to better hemostasis." (PMID 25243020, 2014). "This is contrary to reports that IL-1β has a negative inotropic effect and that it also leads to endothelial dysfunction." (PMID 25598708, 2014). "Even in the absence of bacteremia, cytokine release (IL-6, TNF-α, IL-1β) may induce endothelial dysfunction, increased capillary permeability, and myocardial edema, which could suggest worsening of myocardial involvement by SIRS." (PMID 41466908, 2025).
endothelial dysfunction (continued). "Moreover, TREM-1 activation was shown to result in a persistent release of cytokines and chemokines (tumour necrosis factor alfa [TNF-α], IL-1β, IL-8, and monocyte chemotactic protein [MCP]-1), and is directly related to endothelial dysfunction and platelet activation." (PMID 34195785, 2021). "Elevated levels of IL-1β, secreted by macrophages, were also identified in patients with MMD, and may activate the proliferation of macrophages, endothelial cells, and SMCs, resulting in increased vascular permeability and endothelial dysfunction." (PMID 33567654, 2021). "On the other hand, no role for pro-inflammatory enzymes, such as COX or iNOS, was observed for the endothelial dysfunction evoked by IL-1β, as it was not modified by the inhibition of COX with indomethacin (10 μmol/L) or by the blockade of iNOS with 1400 W (10 μmol/L)." (PMID 25518980, 2014). "Furthermore, TMAO contributes to atherosclerosis and endothelial dysfunction by promoting macrophage cholesterol accumulation and activating pro-inflammatory pathways such as NF-κB and MAPK, which lead to increased expression of adhesion molecules and cytokines (IL-1β, IL-18, TNF-α)." (PMID 41516081, 2025).
inflammatory bowel disease (227 papers, 2009 to 2026). A spectrum of small and large bowel inflammatory diseases of unknown etiology. "In terms of monocytes, apart from the broad susceptibility observed in MHC_II_cMo, IL1B_cMo predispose the risk of inflammatory bowel disease, ITGAM_cMo predispose the risk of psoriatic arthritis, and FADS_cMo predispose the risk of vitiligo." (PMID 40703454, 2025). "IL-1β is also crucial in the inflammatory response associated with inflammatory bowel disease (IBD) and other inflammatory conditions." (PMID 40867896, 2025). "The clinical relevance of this mechanism is underscored by human genetic studies associating ATG16L1 polymorphisms (e.g., T300A) with exaggerated IL-1β and IL-6 production in inflammatory bowel disease." (PMID 41522448, 2025). "The relationship between the ENS, epithelial integrity, and Il1b/Il1ra expression and possible predisposition to inflammatory bowel disease remains an interesting topic for future studies." (PMID 39299667, 2024). "IL17‐producing cells are concentrated in the intestinal mucosa and submucosa of patients with inflammatory bowel disease, and they are functionally linked with a pro‐inflammatory role via the upregulation of TNFα, IL1B, IL6, IL8, and neutrophil recruitment." (PMID 38992956, 2024). "Recently, a study showed that the high expression of IL-1β in the intestinal mucosa was associated with resistance to corticosteroid therapy and treatment with TNFα inhibitors in inflammatory bowel diseases." (PMID 37176572, 2023). "Elevated IL-1β is associated with increased disease severity in patients with inflammatory bowel diseases." (PMID 35294872, 2022). "Nonetheless, we were intrigued about the augmented levels of Il17a and Il1r1 transcripts found in cluster 3 RORγtS182A colonic Th17 cells, as the elevated IL-1β level was associated with increased disease severity in patients with inflammatory bowel diseases." (PMID 35294872, 2022). "IL-1β is another prominent proinflammatory cytokine and its upregulation is implicated in autoimmune disorders, neurologic diseases, vascular diseases, inflammatory bowel diseases, and multiple sclerosis." (PMID 35745829, 2022). "Its succinylation promotes the production of IL‐1β and other pro‐inflammatory cytokines, thus increasing inflammatory bowel disease susceptibility." (PMID 36308411, 2022). "An exaggerated production of cytokines, such as IL-1β and IL-8, can lead to the development of intestinal pathologies linked with a disruption of the intestinal barrier, such as inflammatory bowel disease." (PMID 30670931, 2018). "As pro-inflammatory cytokines, IL-1β and IL-17F have been implicated in the disease pathogenesis, such as inflammatory bowel disease and celiac disease in humans." (PMID 29311620, 2018). "ARNO has been implicated in IL-1β signaling, and given the association of INAVA with inflammatory bowel disease, we examined the effect of IL-1β on INAVA-ARNO function." (PMID 30355448, 2018). "For instance, Nemetz et al13 reported that allelic variation at the IL-1β gene was associated with reduction of bone mass in patients with inflammatory bowel disease." (PMID 20940514, 2010). "TNF-α and IL-1β are pleiotropic pro-inflammatory cytokines, whose dysregulations are linked with a wide range of pathological conditions, such as infection, metabolic syndrome and inflammatory bowel disease." (PMID 35436978, 2022). "Furthermore, the level of inflammatory bowel disease-associated factor IL-1β was also elevated in the ileum, jejunum, and colon." (PMID 33329010, 2020). "Indeed, overproduction of IL-1β was observed in patients with inflammatory bowel disease, and has been connected with deficiency of α-defensins that serve as regulators of IL-1β maturation." (PMID 31877866, 2019). "Other mucosal conditions such as inflammatory bowel disease, which is associated with high gut IL-1β production and partly regulated by IL-3753, may also be modulated by this risk allele." (PMID 30206230, 2018).
inflammatory bowel disease (continued). "This receptor has been largely associated with inflammatory diseases, including inflammatory bowel diseases, and it can signal through caspase-1 to cause the production of pro-inflammatory IL-1β and IL-18, as well as TNF-α and nitric oxide, from inflammatory cells." (PMID 29167643, 2017). "Furthermore, an impaired expression of DEF-5 and LCN2 and the over-production of the pro-inflammatory cytokine IL1β have been closely associated with inflammatory bowel disease." (PMID 23754197, 2013). "Previous studies have directly implicated the presence of TNF, IL-6, and IL-1β proinflammatory cytokines in the pathogenesis of a number of inflammatory diseases, such as inflammatory bowel disease (IBD), rheumatoid arthritis, sepsis, and most importantly, in mucositis." (PMID 22973511, 2012). "Several studies have implicated the role of TNF-α, IL-1β, IL-6 in the pathogenesis of a number of inflammatory diseases, such as inflammatory bowel disease (IBD), rheumatoid arthritis, sepsis and mucositis." (PMID 26618095, 2015). "Prevotella was also found to have an increased oral abundance in inflammatory bowel disease (IBD) patients and was positively associated with the inflammatory cytokine IL1β levels in these patients." (PMID 40077792, 2025). "In a rodent model of inflammatory bowel disease, treatment with Astragalus resulted in a reduction in the activity of interleukin 1 beta (IL-1β) and TNFα, key inflammatory mediators, through inhibiting NF-κB activation and ERK and JNK phosphorylation." (PMID 40284164, 2025). "Some phages have been shown to reduce pro-inflammatory cytokines such as IL-6, TNF-α, and IL-1β, thus alleviating systemic inflammation in diseases like inflammatory bowel disease (IBD) and rheumatoid arthritis." (PMID 40427029, 2025). "Using a novel in vitro model of intestinal organoids, we compared the morphological and functional phenotypes of intestinal organoids in non-inflammatory bowel disease controls with those treated with the inflammatory factor IL-1β." (PMID 40281931, 2025). "FDEVs reduce pro-inflammatory cytokines (IL-1β, IL-6) and increase anti-inflammatory IL-10 levels, demonstrating efficacy in mouse models of inflammatory bowel disease." (PMID 39796048, 2024). "IL-2, IL-1β, IFN-γ, IL-6, TNF-α, and IL-8 is a pro-inflammatory cytokine associated with inflammatory bowel disease, and the pro-inflammatory cytokine response is a critical pathophysiological factor in the acceleration of the occurrence and development of UC." (PMID 39473926, 2024). "IL-6, TNF-α, IL-1β, and IL-10 serve as pivotal pathological mediators in inflammatory bowel disease." (PMID 39187810, 2024). "The studies of Xiao-Yu Ai confirm that apigenin effectively inhibits inflammatory bowel disease and colitis-associated cancer through decreased levels of the inflammatory cytokines TNF-α, IL-1β, IL-6, MCP-1, and CSF-1 and of COX-2 in tumors." (PMID 36836951, 2023). "It is secreted by endothelial cells upon IL-1β stimulation and abundantly secreted in maternal circulation and inflammatory conditions such as inflammatory bowel disease (IBD)." (PMID 38074873, 2023). "It is well-established that IL-1β and TNF-α are among the main pathogenic factors that contribute to damage in conditions such as Crohn’s disease and other inflammatory bowel diseases." (PMID 38249453, 2023). "In line with our finding, IL-1β was also shown to increase NO production by peripheral blood mononuclear cells from healthy donors and inflammatory bowel disease patients." (PMID 35126390, 2022). "In conclusion, this study suggests that the flavonoids, phenolic acids and polysaccharides from chrysanthemum stem and leaf extracts can improve inflammatory bowel disease of zebrafish by regulating the expressions of IL-1β, IL-8 and MMP9." (PMID 35408512, 2022). "Of note, TNF-α, IL-1β, and IL-6 are produced by macrophages in different inflammatory conditions, including inflammatory bowel diseases (IBD)." (PMID 34072532, 2021).